G6PD (glucose-6-phosphate dehydrogenase)
Diseases named in the same sentence as G6PD in open-access papers (continued):
Sharing a sentence is not in itself a finding about the gene and the disease.
cancer (continued). "Drugs that inhibit G6PD activity could not only disrupt cancer cell metabolic homeostasis but also enhance the immune response against tumors." (PMID 40116585, 2025). "To minimize the limitation, we also confirmed whether any change in cancer stage occurred after the measurement of G6PD levels." (PMID 41374996, 2025). "Therefore, further studies are needed to elucidate the mechanisms by which serum G6PD activity increases in parallel with cancer progression." (PMID 41374996, 2025). "Glucose-6-phosphate dehydrogenase (G6PD), which plays an essential role in maintaining intracellular NADPH homeostasis, has recently emerged as a promising biomarker due to its association with cancer stage and progression." (PMID 41374996, 2025). "M. procera exhibited a 94% inhibition of glucose 6-phosphate dehydrogenase in its anticancer mechanism against A549 cancer cells, which is essential for fulfilling the energy and metabolic requirements of glycolysis and the pentose phosphate pathway in cancer cells." (PMID 40142097, 2025). "Furthermore, clinical and cellular studies have confirmed that G6PD can activate signal transducer and activator of transcription 3 (STAT3), which is associated with poor outcomes and the migration and invasion of cancer cells." (PMID 38418897, 2024). "Whether inhibiting G6PD as part of cancer treatment could trigger hemolytic anemia and result in severe side effects remains to be determined." (PMID 39796677, 2024). "We found that G6PD participated in the immune regulation of human cancers via TISIDB database." (PMID 38194707, 2024). "Therefore, to meet their metabolic and bioenergetic requirements, proliferating cancer cells activate G6PD to increase the PPP flux and obtain more NADPH and other resources." (PMID 38739940, 2024). "Further investigation is required to evaluate how these compensatory mechanisms could influence the effectiveness of G6PD inhibitors in cancer treatment." (PMID 39796677, 2024). "Inhibition of autophagy and high expression of the G6PD enzyme are observed in cancer patients." (PMID 39726786, 2024). "Moreover, G6PD regulation is influenced by oncogenic signaling pathways, thus linking genetic alterations to metabolic adaptations in cancer." (PMID 39519266, 2024). "However, AA and glucose 6-phosphate dehydrogenase are directly suppressed by miR-122, thus decreasing glycolysis and arresting cancer cell growth." (PMID 39590305, 2024). "G6PD is known to play a fundamental role in metabolic reprogramming of cancer cells." (PMID 39138186, 2024). "The PPP, particularly its rate-limiting enzyme G6PD, plays a crucial role in cancer metabolism." (PMID 39519266, 2024). "Inhibiting the oxidative PPP and the generation of NADPH through G6PD may trigger compensatory activation of fatty acid oxidation to provide cancer cells sufficient NADPH to survive redox stress." (PMID 39796677, 2024). "In addition, the authors reported that KRT6A overexpression can affect the upregulation of G6PD (glucose-6-phosphate dehydrogenase), resulting in activation of the metabolic pathway promoting invasion and the growth of cancer cells." (PMID 39000463, 2024). "Furthermore, G6PD is a prognostic marker in several cancer types and is also considered to be a tumour target." (PMID 39259139, 2024). "Consequently, upregulated G6PD activity in various cancers significantly contributes to increased NADPH levels, aiding in ROS counteraction and supporting antioxidant systems." (PMID 39519266, 2024). "Therefore, the observed decrease in G6PD expression presents an intriguing approach to combating cancer by regulating cellular metabolism." (PMID 39519266, 2024). "Furthermore, G6PD has become targets for cancer therapy, with recent studies revealing their involvement in cisplatin resistance." (PMID 39025830, 2024).
cancer (continued). "Glucose 6-phosphate dehydrogenase is overexpressed in various cancers, including HCC." (PMID 39590305, 2024). "Inhibition of G6PD induces autophagy through endoplasmic reticulum stress, and it has been reported that cancer therapy may be more effective when G6PD inhibitors, such as polydatin, are used in conjunction with the treatment." (PMID 39726786, 2024). "This suggests that G6PD may represent a promising therapeutic target for immunotherapy in the treatment of these types of cancers." (PMID 37601657, 2023). "However, further intensive investigations are needed to reveal the roles of these novel PTMs in the regulation of G6PD and their impacts on cancer progression." (PMID 38139067, 2023). "G6PD has been associated with increased tumour cell migration, proliferation, invasion, and colony formation capacity, all of which are defined characteristics that lead to EMT in cancer cells." (PMID 37174052, 2023). "G6PD overexpression influences DNA synthesis, regulation of cell cycle, DNA repair, metastasis, invasion and redox equilibrium proliferation to provide a beneficial environment to cancer cells." (PMID 37049781, 2023). "Therefore, the PPP, especially G6PD, has attracted attention as a promising target for cancer therapy." (PMID 38038136, 2023). "Moreover, overexpression of G6PD is also related to stage and degree of cancer, including the tumor size, survival rate, invasion depth, metastasis in lymph node and stage of tumor." (PMID 37049781, 2023). "Thus, the knockdown of hTERT significantly reduces G6PD expression and telomerase activity to promote cancer cell senescence." (PMID 37680899, 2023). "The role of G6PD in cancer is primarily delineated through the end- and by-products of the PPP." (PMID 38139067, 2023). "TAp73 directly activates G6PD to increase PPP flow to inhibit cancer cell senescence." (PMID 37680899, 2023). "G6PD may serve as a potential prognostic biomarker for cancers and may be a potential therapeutic target gene for tumor therapy." (PMID 37601657, 2023). "In addition, G6PD-enhanced activity stimulates resistance to chemotherapeutic drugs in cancer cells." (PMID 37190196, 2023). "Furthermore, the G6PD level was also related to cancer immunity infiltration in most of the cancers, especially in KIRC, LGG, and LIHC." (PMID 37601657, 2023). "Our next step is to experimentally confirm and clarify the role of G6PD in various types of cancer." (PMID 37601657, 2023). "Thus, we evaluated the relationship between G6PD expression and levels of immune infiltration across cancers." (PMID 37601657, 2023). "G6PD expression was upregulated in most cancers compared to their normal counterparts." (PMID 37601657, 2023). "More importantly, G6PD related inhibitors are being studied for cancer treatment." (PMID 38044951, 2023). "The efficacy of cancer drugs is affected by G6PD, therefore leading to drug resistance." (PMID 37049781, 2023). "In addition to promoting cancer cell growth and survival by providing the energy needed for cancer cell proliferation, G6PD’s role in cancer metabolic reprogramming and REDOX signaling was further demonstrated for its role in cancer progression." (PMID 37315289, 2023). "Thus, targeting the PPP is crucial for CRC treatment where many of its enzymes have shown to be potential targets in cancer therapy, among which is the G6PD." (PMID 37190196, 2023). "G6PD is mainly expressed in TAMs, LAPTM4B is predominantly expressed in tumor endothelial cells (TECs), GBA is expressed in both cell populations, and TRAF5 is primarily expressed in cancer-associated fibroblasts (CAFs)." (PMID 38170006, 2023). "Indeed, increasing the PPP flux via G6PD stimulation has been found to trigger cancer progression in a variety of tumor types, coordinate tumor cell cycle progression, promote antioxidant defense and metastasis, and increase drug resistance." (PMID 36977688, 2023).
cancer (continued). "At the same time, G6PD could produce NAPDH to maintain the oxidative balance of cancer cells in the process of glycolysis." (PMID 39188277, 2023). "Therefore, the value of G6PD inhibitors to sensitize G6PD-positive cancer patients to chemotherapy remains elusive." (PMID 36839749, 2023). "Various studies showed that G6PD leads to enhanced cell proliferation in many types of cancers." (PMID 39188277, 2023). "However, the level of G6PD expression in cancer tissues of TGCT was significantly lower compared to the corresponding normal tissues, which was generally counterintuitive since G6PD was highly expressed in testicular tissues." (PMID 37601657, 2023). "The results above imply that G6PD PPI might contribute to cancer progression by regulating signaling pathways related to cell proliferation." (PMID 37601657, 2023). "As an essential enzyme in the pentose phosphate pathway (PPP), G6PD could produce more materials by this pathway to meet the high anabolic needs of tumor cells, which may make the cancers more resistant to chemotherapy." (PMID 38098504, 2023). "Data for G6PD-deficient cancer patients are rare, either because patients are not routinely tested for their G6PD status or because anticancer chemotherapy remains without negative symptoms in these patients." (PMID 36839749, 2023). "Several previous studies revealed the aberrant upregulation of G6PD in various types of cancer." (PMID 38139067, 2023). "In addition to small molecules, several plant extracts have also been identified to have anti-cancer properties that are accompanied by the inhibition of the activity of G6PD." (PMID 36984785, 2023). "High G6PD expression levels are correlated with poorer clinical prognosis in several cancers." (PMID 37601657, 2023). "Overall, these data showed that G6PD might be a prognostic biomarker associated with patient OS, DSS, DFI, and PFI in various human cancers, especially in LIHC." (PMID 37601657, 2023). "We considered whether OBHS affects PPP, a bypass of glycolysis, via the regulation of G6PD as a key process in carcinoma proliferation." (PMID 37108300, 2023). "The dysfunction of G6PD is involved in many diseases, among which cancer is the most common ones." (PMID 35207558, 2022). "The overexpression of G6PD has been described in many types of cancer with poor outcomes." (PMID 35806424, 2022). "However, the roles of G6PD in cancer development mainly depend on its metabolic function in producing NADPH to reduce ROS." (PMID 35207558, 2022). "Therefore, the critical role of enzymatic G6PD in balancing cellular redox in cancer cells is supported by our results and those of other groups." (PMID 36271440, 2022). "A relatively high number of studies have interrogated the role of G6PD in different cancer types but how the overexpression of G6PD contributes to the development of different tumors is largely unknown." (PMID 35433453, 2022). "Also, exploiting a particular mutation can provide an insight to develop structure-based inhibitors against G6PD for cancer cells." (PMID 35368337, 2022). "Indeed, targeting G6PD with inhibitors has been shown to be a promising strategy for the treatment of cancer." (PMID 35806424, 2022). "Furthermore, PFK1 O-GlcNAcylation increases NADPH and GSH levels in cancer cells, and similarly to G6PD, PFK1 O-GlcNAcylation affords a growth advantage to tumor cells." (PMID 36359905, 2022). "Doing so, G6PD sustains the high level of ROS in cancer cells while instigating their survival." (PMID 34975298, 2022).
cancer (continued). "Abnormal activation of G6PD contributes to the progression of many cancers." (PMID 36133439, 2022). "What is more, whether these inhibitors are also efficient in tumors with low G6PD expression, and whether these inhibitors can reverse the chemoresistance of the current clinical drugs in treating cancer are questions that need to be further explored." (PMID 35207558, 2022). "Therefore, DHEA is widely used in cancer research to block G6PD enzyme activity and inhibit the proliferation and migration of cancer cells." (PMID 36091812, 2022). "Altogether, these results confirm the rationale for targeting G6PD activity in cancer." (PMID 35806424, 2022). "G6PD levels have been shown to be elevated in many cancers, and it has been shown that G6PD induces epithelial-mesenchymal transition by activating the signal transducer and activator of transcription 3 pathway, thereby promoting HCC migration and hepatoma cell invasion." (PMID 36347033, 2022). "Though DHEA could induce the apoptosis of cancer cells through G6PD, clinical trials of DHEA have been hampered by the high oral dose required and the hindering in the conversion of DHEA to active androgen." (PMID 35207558, 2022). "The effective dosages and therapeutic durations of G6PD inhibitors in animal models of cancer." (PMID 36091812, 2022). "G6PD expression can be abnormally elevated in a variety of cancers." (PMID 36091812, 2022). "Fluasterone, when compared to DHEA, is also a more potent G6PD inhibitor as well as a more potent anti-glucocorticoid, anti-diabetic and anti-obesity agent, and has at least comparable activity in cancer chemoprevention." (PMID 35371612, 2022). "This implied that networks regulating cancer cells are complicated, and G6PD is a promising target." (PMID 35207558, 2022). "The effective dosages and durations or the application of G6PD inhibitors in cancer cells." (PMID 36091812, 2022). "Therefore, we proposed that stable GSH level maintained by high level of G6PD can enable cancer cells to resist DOX-induced apoptosis, thus conferring metastatic cancer cells with DOX resistance." (PMID 35173543, 2022). "The reverse abnormal expression of G6PD has shown positive effects in inhibiting cancer." (PMID 35207558, 2022). "Thus, targeting G6PD by inhibitors has been shown as a promising strategy in treating cancer and reversing chemotherapeutic resistance." (PMID 35207558, 2022). "There is evidence that glucose-6-phosphate dehydrogenase (G6PD) may be a potential therapeutic target in the treatment of cancer." (PMID 35628385, 2022). "Multiple GSEA analysis of G6PD showed that mTOR signaling, Notch signaling, and cancer pathways were mainly enriched in the high expression group, whereas other metabolic pathways, such as drug metabolism, fatty acid metabolism, and tryptophan metabolism were enriched in the low expression group." (PMID 35938165, 2022). "A recent study observed that in cancers with NRF2 activation, loss of G6PD activity depleted TCA cycle intermediates as a result of increased malic enzyme and isocitrate dehydrogenase activity and increased the dependence on glutamine as a source of TCA cycle intermediates." (PMID 35110412, 2022). "Activation of G6PD plays a pivotal role in cancer proliferation and progression." (PMID 34354953, 2021). "G6PD is expressed at higher rates in cancer cells, which is indicative of greater PPP flux." (PMID 33946927, 2021). "Moreover, in the last years, there is increasing evidence proving that G6PD is a major contributor to invasion, migration, and metastasis in several cancers." (PMID 34572981, 2021). "This evidence has driven in the last years an important ongoing area of investigation devoted to identifying tumors that are particularly sensitive to G6PD inhibition, unveiling an urgent need to explore the impact of tumor microenvironment nutrients on G6PD upregulation in cancer." (PMID 34572981, 2021).
cancer (continued). "Therefore, G6PD has been predicted as a valuable potential target for cancer therapy in the near future." (PMID 34819088, 2021). "Here the proposed model is able to predict that deactivation of glucose-6-phosphate dehydrogenase and ribose 5P isomerase may slow down growth and proliferation of cancer cells." (PMID 33510857, 2021). "G6PD is overexpressed in a number of cancer types 65, including HNSCC." (PMID 33859744, 2021). "The abnormal activation of G6PD leads to proliferation of a variety of cancer cells." (PMID 34819088, 2021). "Moreover, we learn that cancer immunotherapy seems to work well in elderly patients, how thyroid hormones regulate noncoding RNAs in a liver tumour context, and that G6PD is a double-edged sword of redox signalling." (PMID 34091092, 2021). "As an example, consistent with studies in cancer cells, we found that Nrf2 significantly boosted several genes in the pentose phosphate pathway, including those for glucose-6-phosphate dehydrogenase (G6pd), transaldolase 1 (Taldo1), and phosphogluconate dehydrogenase (Pgd)." (PMID 33491671, 2021). "Therefore, G6PD has been proposed as an attractive therapeutic target in the fight against cancer in several studies as it plays an important role in the biosynthesis of ribose and the production of NADPH, which is necessary for the regulation of ROS levels." (PMID 34572981, 2021). "In summary, we demonstrated that G6PD is important for cancer metastasis." (PMID 32719549, 2020). "Indeed, knockdown of G6PD or DHEA increased oxidative stress in cancer cells, resulting in decreased migratory potential and increased susceptibility to cell death under various stresses." (PMID 32487689, 2020). "Increasing evidences including results from our laboratory demonstrated that aberrant expression and activation of G6PD promoted cell proliferation and adaptation in a serial of cancers and might serve as a potential anticancer target." (PMID 33041664, 2020). "PPP is associated with increased cancer cell survival and proliferation, implying the inhibition of phosphofructokinase (mainly PFK1) from glycolysis, a direct competitor of glucose-6-phosphate dehydrogenase (G6PD), the limiting enzyme in PPP." (PMID 32714858, 2020). "The level of G6PD often negatively correlates to the prognosis of cancer patients." (PMID 32582032, 2020). "Up-regulation of the G6PD level or activity is often observed in many kinds of cancer." (PMID 32582032, 2020). "Previous studies have shown that elevated G6PD expression could promote cancer progression in many tumors." (PMID 32903581, 2020). "6-AN, a known competitive inhibitor of G6PD, could modulate the cytotoxicity of antineoplastic treatments, and is undergoing preclinical investigation in certain cancers." (PMID 33041664, 2020). "Taken together, these data suggested that the PI3K/AKT pathway negatively regulates the expression of the E3 ligase TRIM21, which in turn controls the level and activity of the PPP rate-limiting enzyme G6PD via ubiquitin-mediated degradation in vivo and in human cancers." (PMID 32312982, 2020). "As the rate-limit enzyme of the pentose phosphate pathway, glucose-6-phosphate dehydrogenase (G6PD) plays important roles in tumour progression, but the exact mechanism through which G6PD controls cancer metastasis remains unclear." (PMID 32719549, 2020). "Because G6PD has a role to protect cells from cell death, we speculate that its downregulation may lead to oxidative stress-induced immunogenic cell death in cancer cells." (PMID 33361404, 2020).